SOD2 (superoxide dismutase 2)
Diseases named in the same sentence as SOD2 in open-access papers (continued):
Sharing a sentence is not in itself a finding about the gene and the disease.
Hyperglycemia (continued). "More specifically, hyperglycemia downregulated the signature methylation patterns (such as H3K4me1 and H3K4me2) and that can precisely be regulated by lysine-specific histone demethylase 1 (LSD-1) along with Sp1 interactions at the Sod2 promoter." (PMID 30233418, 2018). "Under hyperglycemia, LSD1 could be activated, which reduces H3K4 acetylation in the SOD2 gene, and ultimately induces the development and progression of DR." (PMID 28815013, 2017). "The obtained data demonstrated that hyperglycemia increases trimethyl histone H4 lysine 20 (H4K20me3), acetyl histone H3 lysine 9 (H3K9), and NF-κB p65 at the promoter and enhancer of retinal SOD2, resulting in gene-activating epigenetic changes in MnSOD and decreased expression of SOD2." (PMID 25180070, 2014). "In HMVEC, gene expression of SOD1 and SOD2 (non-significant) simultaneously increased with O2 ̅ levels, and CYBA (non-significant), NOX1, and NOX4 expression during hyperglycemia." (PMID 24093550, 2013). "In the current study, we found that HG increases SOD2, but not SOD1 expression, which might indicate that hyperglycemia preferentially affect H2O2 production in mitochondria." (PMID 26439801, 2015). "However, during the hyperglycemia, the SOD is unable to eliminate the excess ROS, which results in suppression of the antioxidant enzymes such as SOD1, SOD3, and catalase but not SOD2." (PMID 34326888, 2021).
prostate carcinoma (81 papers, 2008 to 2026). A carcinoma that arises from epithelial cells of the prostate gland. "Amongst these genes, we prioritized the SOD2 gene as it has been reported to correlate with prostate cancer risk and prognostic Gleason scores." (PMID 40430023, 2025). "In studies conducted on patients with hormone-dependent cancers such as breast, ovarian and prostate cancer, an increased risk was observed in individuals who had the SOD2-Ala allele." (PMID 36676755, 2023). "Conversely, combining the NRF2 rs6721961 CC genotype with the SOD2 rs4880 C allele increased the risk of prostate cancer development by 4.07 times." (PMID 37062839, 2023). "Men with Ala/Ala genotype in the SOD2 gene (rs_4880) have a higher risk of aggressive prostate cancer in the presence of low antioxidant concentration." (PMID 36648953, 2022). "Previous reports demonstrated that individuals with the SOD2*C/C genotype are at increased higher risk of prostate cancer development, in accordance with the findings of our study." (PMID 36295574, 2022). "A genetic polymorphism in the mitochondrial targeting sequence of the SOD2 gene has been implicated in various diseases, including prostate cancer." (PMID 36648953, 2022). "We also observed that a SNP in SOD2, rs1799725, was associated with increased risk of prostate cancer, with a stronger association for men with low serum levels of retinol." (PMID 35096612, 2021). "This in turn causes reduced expression of SOD2 and increased radiosensitivity of prostate cancer cells." (PMID 34943029, 2021). "SELENOP variants also interact with polymorphisms in the SOD2 gene, which encodes another antioxidant protein, MnSOD, to affect prostate cancer risk." (PMID 32806741, 2020). "A previous study in Macedonian population indicated that SOD2 V16A variant is associated with risk of prostate cancer." (PMID 31929112, 2020). "Increased expression of SOD2 can result in the suppression of prostate cancer cell growth by mediating the senescence-associated tumor suppression with insulin-like growth factor binding protein related protein-1 (IGFBP-rP1)." (PMID 30367578, 2018). "Other researchers identified a higher risk of prostate cancer (odds ratio, 1.16) and increased aggressiveness among Ala alleles of SOD2 exon 2 SNP carriers." (PMID 26881045, 2016). "Moreover, the SOD2 (rs4880) polymorphism increases prostate cancer risk and the odds for high-grade tumors." (PMID 40430023, 2025). "Further, this SOD2 genotype has been implicated in various diseases, including prostate cancer." (PMID 36648953, 2022). "The SOD2 (rs4880) gene polymorphism, alone or in combination with the Nrf2 (rs6721961) gene polymorphism, could serve as a possible biomarker of prostate cancer development." (PMID 36295574, 2022). "Val16A (Ala) SOD2 polymorphism has been associated with increased prostate cancer (PCa) risk." (PMID 33535682, 2021). "Taken together, the current analyses demonstrate that SOD2 V16A variant may be associated with increased susceptibility to urological cancer, especially for prostate cancer." (PMID 31929112, 2020). "It has been demonstrated that SOD2 polymorphism was associated with prostate cancer risk." (PMID 26754536, 2016). "Castration-resistant prostate cancer showed the downregulation of SOD2, which in turn increases ROS; this increased ROS induced androgen receptor activation and promoted resistance to anti-androgen therapy." (PMID 40563571, 2025). "In summary, we propose a novel biological route of Gα13-mediated anchorage-independent growth and response to oxidative metabolic stress through regulation of SOD2 expression in prostate cancer cells." (PMID 40430023, 2025). "This study revealed that superoxide dismutase 2 (SOD2) levels are significantly greater in quiescent prostate cancer (PCa) cells than in proliferative cells." (PMID 40520023, 2025).
prostate carcinoma (continued). "Our previous proteomic and transcriptomic analyses identified superoxide dismutase 2 (SOD2) as the most upregulated molecule in quiescent prostate cancer (PCa) cells." (PMID 40520023, 2025). "To study the effect of Gα13-mediated SOD2 expression in prostate cancer biology, we employed methodologies that are different from previous studies on this topic." (PMID 40430023, 2025). "The mRNA and protein levels of SOD2 were found elevated in samples from patients with middle stage prostate cancer." (PMID 36672191, 2023). "In vitro studies have shown that SOD2 overexpression results in a reduced growth rate of androgen-independent prostate cancer cells." (PMID 36295574, 2022). "This study points out SOD2 as one major regulator for both redox and glycolytic metabolism in prostate cancer." (PMID 35204196, 2022). "In androgen-dependent prostate cancer cells overexpressing SOD2, metabolomics revealed an increase in amino-acid intermediates to provide the bricks that are needed to increase proliferation." (PMID 35204196, 2022). "Overexpression of SOD-2 has been shown to prevent prostate cancer cell proliferation, invasion, and growth." (PMID 35368886, 2022). "We developed and validated a pyrosequencing assay that detects the common germline SOD2 SNP (rs_4880) with the aim of identifying men with castrate-resistant prostate cancer eligible for an antioxidant therapy clinical trial." (PMID 36648953, 2022). "The impact of SOD2 in cancer metabolism in general, and prostate cancer in particular, can be dramatic from a clinical perspective." (PMID 35204196, 2022). "SOD2 induction by RelB is an important mechanism for prostate cancer cells acquiring radioresistance." (PMID 34943029, 2021). "The cg09364756 and cg27624424 methylation were correlated with SOD2 expression in prostate cancer (P < 0.05)." (PMID 31929112, 2020). "The gene-gene interaction of SOD2 among prostate cancer participants was also evaluated by TCGA samples." (PMID 31929112, 2020). "Inhibition of constitutive and radiation-induced NF-κB activity by PN (Section 1) sensitized prostate cancer cells to X-ray, inhibited expression of superoxide dismutase 2 (SOD2) gene and split-dose repair and activated the PI3K-AKT pathway." (PMID 32823992, 2020). "The promoter methylation level of SOD2 was found to be decreased in both Caucasian and Asian prostate cancer participants." (PMID 31929112, 2020). "Plumbagin proved to efficiently induce apoptosis in effect in prostate cancer cell lines, partially through decreasing SOD2 expression." (PMID 27911871, 2017). "A recent study showed that SOD2 expression was sufficient to overcome ROS mediated growth arrest in prostate carcinoma cells." (PMID 25745358, 2015). "SOD2 mRNAs are also targeted by miR-146a and altered expression of SOD2 mRNAs was noted upon overexpression or inhibition of this miRNA in prostate cancer PC12 cells." (PMID 25140888, 2014). "A study has shown that SOD2/catalase and SOD2/GPX1 ratio could be used as biomarkers for prostate cancer, colon cancer, lung cancer, and other tumors." (PMID 37759978, 2023). "In addition, SOD2 was included in functional validation due to its recently reported roles in prostate cancer metabolism and upregulation in other malignancies, while also demonstrating a trend toward increased expression in BPH-1 cells in CAF co-culture." (PMID 36765657, 2023). "Under the light of these new results, we consider that SOD2 metabolism must be further studied in order to define its central role in prostate glucose metabolism, in order to improve management and treatment of prostate cancer." (PMID 35204196, 2022). "Samples from prostate cancer patients were analyzed for SOD2 and GLUT-1 protein expression." (PMID 35204196, 2022).
prostate carcinoma (continued). "The aim of our study was to investigate the possible role of functional polymorphisms of antioxidant enzymes SOD2 and GPX1 and regulatory antioxidant protein Nrf2, alone or combined, in susceptibility to prostate cancer development and overall survival in Serbian male patients." (PMID 36295574, 2022). "However, the noncanonical pathway has been shown to be particularly significant in the induction of SOD2 in prostate cancer." (PMID 34943029, 2021). "Furthermore, prostate cancer subjects with low SOD2 expression had a shorter DFS time than the high-SOD2-expression counterpart." (PMID 31929112, 2020). "To evaluate the correlation of DNA methylation and SOD2 expression, we adopted scatter plots to investigate the relationship between CpG sites and SOD2 expression based on three urological cancers (bladder cancer, prostate cancer, and renal cell carcinoma) in TCGA database." (PMID 31929112, 2020). "As the incidence of prostate cancer (PCa) is associated with aging phenomenon, we further used enzyme linked immunosorbent assay (ELISA) and immunohistochemical staining (IHS) to explore the expression of SOD2 among PCa participants enrolled in our centers." (PMID 31929112, 2020). "Moreover, the expression of SOD2 was found to be downregulated in more advanced prostate cancer participants, as compared to the less advanced ones." (PMID 31929112, 2020). "In addition, prostate cancer subjects with low SOD2 expression had a shorter DFS time than high-SOD2-expression counterparts (P = 0.047)." (PMID 31929112, 2020). "These earlier studies have provided evidence that variants in a combination of the SEPP1 and manganese superoxide dismutase (SOD2) genes affects disease risk, that rs1050450 in GPX1 affects the influence of Se status on risk and that variants in SEP15 affect prostate cancer survival." (PMID 23133653, 2012). "Interestingly, patient data support the notion that superoxide dismutase 2 (SOD2) may function in oncogenesis in some prostate cancers." (PMID 40430023, 2025). "However, TCGA samples showed more than 24 genes to be correlated with SOD2 in prostate cancer." (PMID 31929112, 2020). "In fact, a recent study demonstrated SOD2-driven increased AMPK phosphorylation at Thr172 in breast, colon, and prostate cancers, suggesting the involvement of SOD2 in the glycolytic switch in cancer progression that may represent a mechanism to regulate the Warburg effect." (PMID 29478325, 2019). "Treatment with 50 nM 1,25(OH)2D3 increased the production of SOD1 and SOD2 in prostate epithelial cells (PEC) and androgen-sensitive prostate cancer cells (LNCaP)." (PMID 41009006, 2025). "In prostate cancer, CPT1A promotes cell survival by modulating ROS production in the mitochondria, by upregulating superoxide dismutase 2 (SOD2)." (PMID 38610991, 2024). "SOD2 has recently been shown to increase the GLUT-1 and glucose uptake, which is essential for prostate cancer cell survival." (PMID 36672191, 2023). "This study found that both PIN and prostate cancer had lower SOD1, SOD2, and catalase than benign tissue, results that support data reported earlier." (PMID 34943029, 2021). "The superoxide dismutase (SOD) family consists of SOD1, SOD2, and SOD3 proteins that neutralize the first oxygen-derived ROS and provide protection against the development of cancers, including prostate cancer." (PMID 34943029, 2021). "This suggests that certain prostate cancer cells are under higher ROS stress despite lower OXPHOS activity, and thus require higher expression of SOD2." (PMID 32103057, 2020). "Similarly, in prostate cancer, studies have shown that genes involved in oxidative stress response, such as SOD2 (superoxide dismutase 2) and CAT (catalase), play critical roles in determining the tumor’s response to radiotherapy." (PMID 40652278, 2025). "MiR-17 reduced superoxide dismutase 2 (SOD2 or MnSOD) and GPX in prostate cancer cells." (PMID 36831498, 2023).
prostate carcinoma (continued). "This knowledge provides the unique opportunity to investigate methods that would block SOD2 in prostate cancer but not in normal tissues." (PMID 34943029, 2021). "However, significant decreases in SOD2 expression of introns were observed in LNCAP and PC3 prostate cancer cells." (PMID 26805894, 2016). "However, homozygous SOD2 (rs4880) was not predictive of prostate cancer recurrence or overall survival after radical prostatectomy." (PMID 40430023, 2025). "In addition to SOD2, miR-17-3p also targets GPX2 in prostate cancer cells." (PMID 34199590, 2021). "For prostate cancer, the SOD2 protein, but not the mRNA, increased." (PMID 34943029, 2021). "Our group has previously shown that SOD2 might maintain prostate cancer survival in absence of androgens, and also substantial differences in tumor oxygenation rate between androgen-dependent and -independent prostate cancers have been described." (PMID 35204196, 2022). "Importantly, this regulation seems to be present in prostate cancer patients, as we have observed a very strong correlation (p-value below 0.0001) between SOD2 and GLUT-1 protein in prostate cancer samples from patients, indicating that wherever SOD2 is high, so is GLUT-1." (PMID 35204196, 2022).
Obesity (68 papers, 2007 to 2025). Accumulation of substantial excess body fat. "A total of 1675 children with normal weight and 1271 children with obesity were included to assess the association of four SNPs, SOD2 rs4880, GPX7 rs835337, GPX1 rs1050450, and CAT rs1001179, with obesity." (PMID 40867795, 2025). "Because SIRT6 regulates ENDOG/SOD2, it helps reduce myocardial oxidative stress caused by obesity resulting from a high-fat diet." (PMID 41567643, 2025). "Along these lines, SOD2 rs4880, which has been linked to obesity, is reported to influence the anti-inflammatory properties of resveratrol." (PMID 38281958, 2024). "There have been correlations with increased risk for hepatotoxicity including, obesity, genotype (SOD2 rs4880 CC), and Hispanic ethnicity." (PMID 35844739, 2022). "The difference in BMI values, being on the brink of statistical significance (p ≈ 0.0673) suggests a possible association of rs4880 (SOD2) with obesity." (PMID 32709094, 2020). "Heterozygous deletion of SOD2 has been shown to cause impaired insulin secretion in a mice model of obesity." (PMID 31781116, 2019). "Accordingly, transplantation of genetically modified SOD2-overexpressing mesenchymal cells has been suggested as a new therapeutic approach for obesity-associated metabolic syndrome." (PMID 27399681, 2016). "Several SNPs of the NRF2 gene have repercussions on certain antioxidant enzymes, for example, rs2234694 is related to SOD1, rs2536512 to SOD3, rs1056806 to GSTM1, rs4880 to SOD2 and rs1800668 to GPx1; all were found in obese patients and were associated with increased risk of obesity." (PMID 40428311, 2025). "Consequently, we propose that further investigations be conducted to explore the anti-obesity effects of resveratrol by focusing on relevant genetic profiles, including SOD2, BDNF, PPAR, NR1I3 and MTNR1B polymorphisms." (PMID 38281958, 2024). "When adolescent female mice were subjected to a prolonged duration (26 weeks) of HFD, both SOD1 and SOD2 activities were significantly lower in all three brain subregions compared to their respective controls, underlining the marked effect of obesity duration." (PMID 39230054, 2024). "However, mice with adipocyte-specific SOD2 deficiency exhibited resistance to HFD-induced obesity and enhanced energy expenditure." (PMID 37627590, 2023). "Genotypic variability of SNP rs4880 (SOD2) may be associated with obesity, as the C/T genotype was observed in over 90% of obese individuals." (PMID 32709094, 2020). "A role for oxidative stress in the development of T2D has been largely supported by several studies; however, oxidative damage is also associated with obesity, can also be prevented by overexpression of CuZn- or Mn-superoxide dismutase (SOD1 and SOD2, respectively)." (PMID 33375647, 2020). "For the SNPs − 21A>T CAT (rs7943316), − 262C>T CAT (rs1001179), and 47C>T SOD2 (rs4880), we identified differences between people with obesity CR (homozygous plus heterozygous) of mutated allele, and obese WT people, with respect to anthropometric and clinical variables in a cross-sectional study." (PMID 29339975, 2018). "Interestingly, the C/T genotype of another SNP, the rs4880 (SOD2), occurred in more than 90% of the obese group, indicating that this polymorphism might be a hereditary factor for developing obesity." (PMID 32709094, 2020). "Previous studies have reported associations of SNPs SOD2 rs4880, GPX7 rs835337, GPX1 rs1050450, CAT rs1001179 with obesity, body mass index and body fat in Brazilian, Mexican, British, Finnish, Chinese, Caucasian, and African–American adult populations." (PMID 40867795, 2025). "In previous studies, the SNPs SOD2 rs4880, GPX7 rs835337, GPX1 rs1050450, and CAT rs1001179 have been associated with lipid peroxidation, obesity, and their metabolic complications in adult populations." (PMID 40867795, 2025). "In this study, HFHS-induced obesity alone decreased both superoxide dismutase 2 (SOD2) and hemopexin (HPX1)." (PMID 39910959, 2025).